PCDHGB2 (protocadherin gamma subfamily B, 2)
Description:
Potential calcium-dependent cell-adhesion protein. May be involved in the establishment and maintenance of specific neuronal connections in the brain.
Synonyms: PCDH-gamma-B2
Tractability: Antibody: UniProt places it where antibodies can reach, with medium confidence; UniProt predicts a signal peptide or a membrane-spanning region; its Gene Ontology location is reachable by antibodies, with medium confidence; the Human Protein Atlas places it where antibodies can reach.
Gene: Protein-coding gene on chromosome 5 (141,359,994 to 141,512,975, forward strand). Ensembl gene ENSG00000253910.
Subcellular location: Cell membrane
Subcellular location (Human Protein Atlas): Cytosol; Plasma membrane; Vesicles; Nucleoplasm
Gene Ontology:
Molecular function: cell adhesion molecule binding; calcium ion binding
Biological process: cell adhesion; homophilic cell-cell adhesion
Cellular component: cytosol; plasma membrane; membrane
Genetic constraint (gnomAD): Loss-of-function variants: 55 observed, 62.44 expected, observed/expected ratio (o/e) 0.88, 90% interval 0.71 to 1.1. The upper end of that interval is the gene's LOEUF score, 1.1, which puts it in group 4 of 6, group 1 being the genes least tolerant of losing a copy. Missense variants: 1,228 observed, 1,258.3 expected, observed/expected ratio (o/e) 0.98, 90% interval 0.93 to 1.02. Synonymous variants: 516 observed, 530.11 expected, observed/expected ratio (o/e) 0.97, 90% interval 0.9 to 1.05.
Homologues: Orthologues: mouse Pcdhgb2 (82% identical). Paralogues in human: PCDHGB1 (75% identical), PCDHGB5 (72% identical), PCDHGB3 (70% identical), PCDHGB7 (70% identical), PCDHGB6 (70% identical), PCDHGB4 (69% identical), PCDHGA6 (52% identical), PCDHGA12 (51% identical), PCDHGA7 (51% identical), PCDHGA5 (51% identical), PCDHGA1 (51% identical), PCDHGA10 (51% identical), and 49 more.
Diseases named in the same sentence as PCDHGB2 in open-access papers:
PCDHGB2 is named in the same sentence as 5 diseases in open-access papers, as found by Europe PMC text mining. Sharing a sentence is not in itself a finding about the gene and the disease. The quoted sentences say what the papers report.
prune belly syndrome (1 paper, 2023). "PCDHGB2 gene is associated with the very rare Prune Belly Syndrome (ORPHA 2970), where patients exhibit deformations in the musculoskeletal, renal and urinary systems." (PMID 37160609, 2023).
gastrointestinal disease (1 paper, 2025). A disease that occurs in the gastrointestinal system, excluding the hepatobiliary system. "Cg11014124, located on the shelf of CpG islands, is linked to PCDHGB2, a gene associated with gastrointestinal diseases." (PMID 40558028, 2025).
tumor (1 paper, 2015). "Here, subtype‐specific events involving either DNA copy number loss or CpG promoter methylation were found to involve TENC1, RARA, PCDHB11, PCDHB14, PCDHGA2 and PCDHGB2 indicative of candidate tumor suppressor genes in this context." (PMID 25468711, 2015).
PCDHGB2 also shares sentences with these, for which no sentence is quoted: anemia (1 paper); hydronephrosis (1).